CRP (C-reactive protein)
Diseases named in the same sentence as CRP in open-access papers (continued):
Sharing a sentence is not in itself a finding about the gene and the disease.
hip fracture (continued). "This study examined the association of 25-hydroxyvitamin D (25(OH)D) and C-reactive protein (CRP) with postoperative medical complications and one year mortality of elderly patients sustaining a low-energy cervical hip fracture scheduled for surgery." (PMID 26833068, 2016). "In addition, there were significant, although weak, correlations between the 25(OH) D levels and those of high-sensitivity C-reactive protein (r = −0.162, P = 0.002) and Ca (r = 0.202, P < 0.0001) in hip fracture patients." (PMID 26699707, 2015). "In addition, elevated CRP and ferritin, which are common inflammatory markers determined in routine clinical practice, could successfully predict 30-day mortality after hip fracture." (PMID 34794459, 2021). "Recently, some inflammatory markers, such as interleukin-6 (IL-6), C-reactive protein (CRP), prognostic nutritional index ratio (PNI), CRP/PNI ratio, and neutrophil-to-lymphocyte ratio (NLR) were found to be independently associated with increased early and long-term mortality after hip fracture." (PMID 33663402, 2021). "Our machine-learning models identified BNP, Troponin T, CRP, CK-MB, and other laboratory markers as the most important predictors of POD in hip fracture patients in the whole dataset." (PMID 38267405, 2024). "No consensus has been reached on the correlation between CRP and hip fracture mortality." (PMID 36894998, 2023). "This may explain why nonsurvivors of hip fracture in our meta-analysis simultaneously presented with a lower albumin level and higher CRP level." (PMID 36894998, 2023). "In our study, following hip fracture, nonsurvivors were older and had a higher CRP level, suggesting that age may simultaneously correlate with higher baseline CRP level and higher mortality risk in patients with hip fracture." (PMID 36894998, 2023). "Third, many confounding factors relating to CRP level and hip fracture mortality such as age, gender, and comorbidities were not adequately controlled for at baseline in some of the included studies, which may have adversely affected with the results of our meta-analysis." (PMID 36894998, 2023).
leptospirosis (28 papers, 2012 to 2026). A contagious bacterial infection caused by spirochetes of the genus Leptospira. "However, reduced procalcitonin and CRP were significantly associated with dengue infection compared to leptospirosis and rickettsiosis." (PMID 35622704, 2022). "CRP rise in leptospirosis is indicative of the bacterial infection–induced systemic inflammatory response." (PMID 39610672, 2024). "A strong inflammatory response, which is common in leptospirosis, is indicated by elevated CRP levels." (PMID 39610672, 2024). "Under sampling conditions, the post-test probability of having leptospirosis with CRP <50mg/L was 1% [CI 95% (0 to 2)]." (PMID 37195992, 2023). "This comparative study shows that the use of CRP alone with a cut-off value of 50mg/L is an effective biomarker to differentiate leptospirosis from DF before laboratory confirmation is received." (PMID 37195992, 2023). "On admission, the values of the following parameters were significantly higher in leptospirosis patients compared to DF sufferers: leukocyte count, neutrophil count, monocyte count, creatinine, urea, bilirubin, creatine kinase and CRP." (PMID 37195992, 2023). "According to our study and a previous retrospective study in French Guiana, high CRP seems to be a valuable biomarker in order to differentiate leptospirosis from DF." (PMID 37195992, 2023). "In Le Turnier at al., CRP used alone was almost as performant as the multi-parametric model used for the presumptive diagnosis of leptospirosis." (PMID 37195992, 2023). "There is increasing interest in the role of biomarkers in the diagnosis of acute leptospirosis, and rapid, near-to-care C-reactive protein (CRP) and procalcitonin (PCT) testing is becoming more widely available." (PMID 35456070, 2022). "Previously, the association between long pentraxin PTX3, the protein that is in the same class as C-reactive protein, and mortality in severe leptospirosis was reported, where the serum PTX3 and IL-6 levels were higher in non-survivors." (PMID 33175842, 2020). "Regarding to laboratory findings, elevated sedimentation and LDH was observed in all patients with leptospirosis while 10 to 12/14(71.4–85.7 %) patients had pathological values of CRP, platelets, AST, CK, ALT and leukocytes that followed the severity of clinical manifestation." (PMID 37223056, 2023). "In the setting of an early presumptive diagnosis, we found that an increased CRP value (>50 mg/L) could help diagnose leptospirosis and aid the decision process for hospital surveillance and/or a potential antibiotic treatment regimen." (PMID 37195992, 2023). "In the multivariate analyses, the main parameters associated with leptospirosis were: i) increased neutrophil counts, ii) C-reactive protein values, iii) the absence of prolonged partial thromboplastin time, and iv) a decrease of platelets." (PMID 37195992, 2023). "High CRP biomarker has been described in severe leptospirosis." (PMID 35622704, 2022). "Standard biomarkers such as C-reactive protein (CRP) and procalcitonin have relatively low specificity for leptospirosis." (PMID 34673833, 2021). "This total absence of inflammation in patients with leptospirosis was unexpected because of the elevated levels of CRP, considered as an inflammatory marker of leptospirosis and bacterial infections that correlate with IL-6." (PMID 40986630, 2025). "However, in this study, the comparison of biomarkers between these infections demonstrated that the median CRP and PCT plasma levels were higher in leptospirosis than in rickettsiosis." (PMID 35622704, 2022). "Leptospirosis presents with protean and nonspecific manifestations along with nonspecific findings in routine laboratory investigations, such as increases in CRP, CK, creatinine and transaminases, and thrombopenia." (PMID 33871688, 2021).
leptospirosis (continued). "In leptospirosis, PCT normalises upon treatment in 4 days and CRP within 7 days in non-severe cases and both return to normal in 7 days in severe infections, suggesting greater sensitivity of PCT than of CRP to infection severity, in line with our data." (PMID 23762396, 2013). "However, in the context of emergency management, these two parameters (neutrophil count and bilirubin) have not matched the performance of CRP for presumptive diagnosis of leptospirosis because they add none or little useful information compared to CRP alone." (PMID 37195992, 2023).
generalized anxiety disorder (27 papers, 2015 to 2025). An anxiety disorder characterized by excessive and difficult-to-control worry about a number of life situations. "One study of US adolescents has looked at the association between CRP and symptoms of generalized anxiety disorder GAD." (PMID 35292108, 2022). "Another study has reported association between serum CRP levels and generalised anxiety disorder both assessed at age 15 years." (PMID 29140226, 2018). "Additionally, a cross-sectional study within the UK Biobank found an association between CRP concentrations greater than 3 mg/L and both panic and generalized anxiety disorders." (PMID 39452916, 2024). "For example, previous cross-sectional research using the ALSPAC cohort found a linear, dose-response relationship between serum CRP and generalized anxiety disorder at age 16 years." (PMID 40823322, 2025). "Further increases in c-reactive protein levels were observed in generalized anxiety disorder patients." (PMID 32906843, 2020). "For instance, elevated levels of pro-inflammatory markers, including IL-1β, IL-6, TNF-α, and C-reactive protein (CRP), have been reported in various anxiety-related disorders, such as post-traumatic stress disorder, generalized anxiety disorder, and panic disorder." (PMID 41268373, 2025). "The raised CRP levels was mainly found in subjects with generalized anxiety disorder (GAD)." (PMID 37344456, 2023). "C-reactive protein levels, which are increased following interleukin 6 secretion, were observed to be elevated in a large cohort of individuals diagnosed with panic disorder, agoraphobia, and generalized anxiety disorder." (PMID 32906843, 2020). "Levels of CRP may be elevated in patients with generalized anxiety disorder (GAD) compared to controls, and concentrations may increase over time for patients with agoraphobia." (PMID 32272662, 2020). "CRP levels in blood, serum or plasma samples was significantly raised in generalized anxiety disorder (GAD) patients by meta-analysis, and IFN-γ and TNF-α levels were significantly increased in at least two or more studies." (PMID 34440101, 2021). "For example, significantly elevated levels of CRP, IFN-γ and TNF-α were found in patients with Generalized Anxiety Disorder (GAD) compared with healthy controls." (PMID 39624485, 2024). "Moreover, regression analysis was conducted to evaluate the possible effect of interaction between gut microbiome and CRP on the risks of Patient Health Questionnaire-9 (PHQ-9) (N = 113,693) and Generalized Anxiety Disorder-7 (GAD-7) (N = 114,219)." (PMID 34481527, 2021). "Notably, elevated concentrations of inflammatory signals, including cytokines and C-reactive protein, have been reported in patients with PTSD, generalized anxiety disorder, and depression." (PMID 33051440, 2020).
gingivitis (27 papers, 2009 to 2025). A disorder involving inflammation of the gums; may affect surrounding and supporting structures of the teeth. "In this study, patients with gingivitis had higher salivary and serum CRP levels than those in the control group; however, the difference was not significant." (PMID 36192745, 2022). "Salivary CRP level was higher in the gingivitis group (793.4 pg/ml) than control (637.2 pg/ml) group, but the difference was not significant." (PMID 36192745, 2022). "In this study, the suPAR and CRP levels were correlated in the saliva of the gingivitis group." (PMID 36192745, 2022). "Also, in some of subjects of the healthy group, salivary CRP concentrations were close to the gingivitis group." (PMID 24551806, 2013). "Second, chronic inflammation at extraarticular sites (e.g., gingivitis) might stimulate CRP production." (PMID 19606218, 2009). "Clinical interventions for severe gingivitis have demonstrated reductions in oral TNF-α and CRP, while advanced gingivitis also correlates with elevated IL-1β in saliva." (PMID 40558433, 2025). "For participants who received JNJ-63733657 15 mg/kg, the most common TEAEs were nasopharyngitis (33%) and gingivitis (33%), and for participants who received JNJ-63733657 60 mg/kg, the most commonly reported TEAE was C-reactive protein increase (33%)." (PMID 39559872, 2024). "The present study is the first report that demonstrated elevated serum levels of CRP, IL-6 and MCP-1 in the course of experimental gingivitis." (PMID 23408963, 2013).
iron overload (27 papers, 2008 to 2026). "In adults, iron overload is associated with increases in complement C3 and C-reactive protein (CRP), an acute phase reactant in inflammation and infection and regulated by IL-6." (PMID 30836628, 2019). "Also, the diagnostic performance of GDF-15 as a marker of inflammation in CKD was comparable to CRP and better than ferritin that is mostly elevated by iron overload associating CKD, qualifying GDF-15 as a surrogate marker of inflammatory status in CKD." (PMID 37649102, 2023). "While residual confounding remains a possibility, our finding that high plasma ferritin remained significantly associated with poor clinical outcomes after accounting for CRP concentrations provides support for the clinical importance of iron overload in TB progression." (PMID 22606361, 2012). "While findings support routine SF screening but highlight the need for future studies incorporating inflammatory markers (e.g., CRP) and systematic transfusion histories to definitively quantify the iron overload burden in this population." (PMID 42201936, 2026). "But serum ferritin is also increased in acute and chronic inflammation, and, in order to diagnose the iron overload, we would also need a measurment of the C-reactive protein level and total iron binding capacity in the serum." (PMID 29696062, 2018). "In dialysis children and adolescents with iron overload, ferritin levels showed a positive correlation with CRP, IL-6 and LVM." (PMID 30150549, 2018). "Biochemical markers of iron overload (namely serum ferritin and transferrin saturation), as well as CRP levels, were significantly higher in MDS patients as compared to controls." (PMID 21886780, 2011). "Although this study measured CRP levels, the specificity of SF as an indicator of iron overload remains confounded by inflammatory status (e.g., CRP elevation may drive SF increases)." (PMID 41204483, 2025). "In addition, in dialysis children and adolescents with iron overload, ferritin levels showed a positive correlation with inflammation markers (CRP and IL-6) and left ventricular mass (LVM)." (PMID 30150549, 2018). "We recommend to assess the serum ferritin level and transferrin saturation together with liver enzymes and inflammation markers such as fibrinogen or C-reactive protein = CRP as a simple (and non-invasive) initial diagnostic step, in order to determine or exclude iron overload." (PMID 18218040, 2008). "Importantly, because CRP, hepcidin, and related inflammatory/iron-regulatory markers were not available, we cannot reliably distinguish inflammation- or congestion-driven ferritin elevations from true iron overload in this dataset." (PMID 41517493, 2025). "Although adjustments for albumin and C-reactive protein were tried to screen out highly inflammatory status as a cause of high ferritin, we cannot completely exclude causes of high ferritin other than iron overload due to lack of thorough clinical information about these factors." (PMID 36650247, 2023). "However, because CRP, hepcidin, and related inflammatory/iron-regulatory biomarkers were unavailable, we could not reliably distinguish inflammation- or congestion-driven ferritin elevations from true iron overload at the individual level." (PMID 41517493, 2025). "Second, lack of inflammatory markers (CRP, IL-6) prevents distinguishing ferritin elevation from inflammation versus true iron overload." (PMID 41470856, 2025).
pneumonitis (27 papers, 2013 to 2025). An inflammatory process affecting the lung parenchyma. "Univariate analysis indicated that age, IIPs, PD‐L1, WBC count, eosinophil count, monocyte count, and albumin and C‐reactive protein (CRP) levels were risk factors for ICI pneumonitis." (PMID 33201587, 2021). "Various cytokines have been associated with the development of irAEs, with C-reactive protein (CRP), IL-6, and IL-17 being related to pneumonitis." (PMID 41303899, 2025). "In a case report, the baseline CRP level increased from 14.2 to 138.9 mg/L when pneumonitis occurred." (PMID 35756643, 2022). "In this case, grade 5 inflammation marker C-reactive protein and pneumonitis presented the day after a three-dose treatment." (PMID 33110170, 2020). "Moreover, females had a greater presentation of an increase in the CRP level (42.8%), serum ferritin (14.2%), PT (42.8%), lymphocyte (28.6%), and X-ray (mild features of pneumonitis) (14.2%) during the follow-up." (PMID 34490284, 2021). "Furthermore, we have also shown elevated levels of interleukin-6 (IL-6) corresponding to elevated CRP in a patient with pneumonitis." (PMID 31277704, 2019). "The analysis revealed higher hs-CRP and PCT levels in patients with CAP infected with bacteria than in those in the groups with other types of CAP but lower levels than those in the group with pneumonitis." (PMID 37180431, 2023). "Clinical characteristics and biomarkers, such as serum CRP, PCT, and albumin levels measured during the first 24 h, were not useful to differentiate BAP from pneumonitis." (PMID 36431150, 2022). "However, they compared BAP versus no BAP (including pneumonitis and absence of aspiration syndrome), and the results could be biased by the presence of patients without aspiration syndrome who do not have increased serum levels of CRP and PCT." (PMID 36431150, 2022). "Unlike pneumonitis, there were no signs of inflammation as shown by the elevated NLR or CRP levels during the developing endocrine irAE—even though the thyroid and pituitary should be attacked by activated immune cells." (PMID 33446685, 2021). "Intriguingly, common inflammatory biomarkers, including C-reactive protein (CRP) and neutrophil/lymphocyte ratio (NLR), were not consistently increased during the onset of CITD but were substantially increased during the onset of pneumonitis and intestinal perforation irAEs." (PMID 36568170, 2022).